MLLT3 (MLLT3 super elongation complex subunit)
Description:
Chromatin reader component of the super elongation complex (SEC), a complex required to increase the catalytic rate of RNA polymerase II transcription by suppressing transient pausing by the polymerase at multiple sites along the DNA. Specifically recognizes and binds acylated histone H3, with a preference for histone H3 that is crotonylated. Crotonylation marks active promoters and enhancers and confers resistance to transcriptional repressors. Recognizes and binds histone H3 crotonylated at 'Lys-9' (H3K9cr), and with slightly lower affinity histone H3 crotonylated at 'Lys-18' (H3K18cr). Also recognizes and binds histone H3 acetylated and butyrylated at 'Lys-9' (H3K9ac and H3K9bu, respectively), but with lower affinity than crotonylated histone H3. In the SEC complex, MLLT3 is required to recruit the complex to crotonylated histones. Recruitment of the SEC complex to crotonylated histones promotes recruitment of DOT1L on active chromatin to deposit histone H3 'Lys-79' methylation (H3K79me). Plays a key role in hematopoietic stem cell (HSC) maintenance by preserving, rather than conferring, HSC stemness. Acts by binding to the transcription start site of active genes in HSCs and sustaining level of H3K79me2, probably by recruiting DOT1L. Required for DOT1L-mediated H3K79 hypermethylation at the SCNN1A promoter, resulting in transcriptional repression (By similarity). May play a role in leukemogenic gene transcription.
Synonyms: AF9; YEATS3; AF-9
Tractability: Small molecule: a structure with a bound ligand is known; a high-quality ligand is known. PROTAC: UniProt records ubiquitination sites on it; ubiquitination databases record sites on it; a small molecule that binds it is known.
Target class: YEATS domain; Epigenetic regulator; Reader
Chemical probes: NVS-MLLT-1 (high quality), PFI-6 (high quality), PFI-8 (high quality), SGC-iMLLT (high quality), SR-0813 (high quality)
Gene: Protein-coding gene on chromosome 9 (20,341,669 to 20,622,499, reverse strand). Ensembl gene ENSG00000171843.
Subcellular location: Nucleus; Chromosome
Subcellular location (Human Protein Atlas): Nucleoplasm; Cytosol
Pathways (Reactome):
Gene expression (Transcription): Formation of RNA Pol II elongation complex; RNA Polymerase II Pre-transcription Events; RNA Polymerase II Transcription Elongation
Gene Ontology:
Molecular function: chromatin binding; histone binding; histone H3K18ac reader activity; histone H3K27ac reader activity; histone H3K9ac reader activity; modification-dependent protein binding; molecular adaptor activity; protein binding
Biological process: hematopoietic stem cell differentiation; negative regulation of canonical Wnt signaling pathway; positive regulation of DNA-templated transcription; positive regulation of Wnt signaling pathway, planar cell polarity pathway; regulation of chromatin organization; regulation of stem cell division; chromatin organization
Cellular component: chromosome; extracellular exosome; nucleoplasm; nucleus; transcription elongation factor complex
Genetic constraint (gnomAD): Loss-of-function variants: 3 observed, 46.41 expected, observed/expected ratio (o/e) 0.0646, 90% interval 0.028 to 0.17. The upper end of that interval is the gene's LOEUF score, 0.17, which puts it in group 1 of 6, group 1 being the genes least tolerant of losing a copy. Missense variants: 537 observed, 659.05 expected, observed/expected ratio (o/e) 0.81, 90% interval 0.76 to 0.88. Synonymous variants: 260 observed, 222.74 expected, observed/expected ratio (o/e) 1.17, 90% interval 1.05 to 1.29.
Homologues: Orthologues: chimpanzee MLLT3 (100% identical), rabbit MLLT3 (99% identical), mouse Mllt3 (99% identical), rat Mllt3 (99% identical), pig MLLT3 (98% identical), dog MLLT3 (98% identical), macaque MLLT3 (90% identical), tropical clawed frog mllt3 (76% identical), zebrafish mllt3 (62% identical), Drosophila melanogaster ear (36% identical). Paralogues in human: MLLT1 (54% identical), YEATS2 (24% identical).
Diseases named in the same sentence as MLLT3 in open-access papers:
MLLT3 is named in the same sentence as 80 diseases in open-access papers, as found by Europe PMC text mining. Sharing a sentence is not in itself a finding about the gene and the disease. The quoted sentences say what the papers report.
leukemia (417 papers, 2006 to 2026). A malignant (clonal) hematologic disorder, involving hematopoietic stem cells and characterized by the presence of primitive or atypical myeloid or lymphoid cells in the bone marrow and the blood. "Noteworthy, the observed shift of KMT2A breakpoints towards intron 11 in the adult patient group with MLLT3 fusions was clearly linked to therapy-induced leukemia." (PMID 37019990, 2023). "The fifth transcript was linked to MLLT3 (protein AF‐9), which has been associated with leukemia in several vertebrate species." (PMID 32821278, 2020). "Mllt3 (AF9) plays roles in hematopoietic differentiation into megakaryocyte and erythroid lineages and as a translocation partner with Mll causes leukemia via a leukemic stem cell mechanism." (PMID 20098702, 2010). "M4 represents acute myelomonocytic leukemia, while M5, or monocytic leukemia, often presents with poor prognosis, extramedullary disease, and abnormalities on chromosome 11q, including the MLLT3 (MLL-AF9) fusion protein, causing the Mixed-Lineage Leukemia (MLL) subtype." (PMID 39200378, 2024). "Similarly, the MLLT3 (mixed lineage leukemia, translocated to 3, also known as AF9) gene is a critical regulator of hematopoietic stem cell self-renewal, and also implicated in leukemias." (PMID 32414213, 2020). "The cell-of-origin and the mechanisms driving lineage choice in KMT2A::MLLT3+ infant leukaemia are poorly understood." (PMID 41545699, 2026). "KMT2A::MLLT3 is among the most common translocations initiating leukaemia in infants, where it can manifest with a myeloid or lymphoid leukaemia phenotype." (PMID 41545699, 2026). "In vivo, the study showed that the overexpression of miR-30e delays the development of KMT2A::MLLT3-driven leukemia." (PMID 40282406, 2025). "Certain fusion genes are associated with distinct subtypes of leukemia such as KMT2A::AFF1 and KMT2A::MLLT3 (also known as MLL-AF4 and MLL-AF9, respectively)." (PMID 39858509, 2025). "MLLT3, frequently involved in gene fusions in leukemia and glioblastoma, presents a promising treatment target, given its oncogenic role and potential regulation of the JNK signaling pathway." (PMID 38534332, 2024). "AF9, also known as MLLT3, is one of the most common fusion partners of the MLL gene, and is often associated with leukemia." (PMID 35615272, 2022). "After the breakthrough discovery of oncogenic f-circRNAs in leukemia with KMT2A::MLLT3 (MLL::AF9), followed by the finding of f-circRNAs in other malignancies with different translocations, no data emerged about chimeric circRNAs in leukemias with other rearrangements involving the KMT2A gene." (PMID 36585787, 2023). "In addition to fluorescence reporter gene integration, we also designed Cre gene integration in two neuron-specific expressed genes (Calcr, Lypd1) and LoxP integration in one leukemia-related gene (Mllt3)." (PMID 37353834, 2023). "Similarly, expression of MLLT3 and MLLT11 genes that are well studied in leukemia are also found to be strongly associated with the survival of CCA patients." (PMID 33193605, 2020). "The third example of AML-causing translocation are MLL (mixed lineage leukemia)-rearranged leukemias such as the fusion protein MLL-AF9 where the N-terminal part of the MLL gene is fused to AF9 (also known as MLLT3), a protein with a role in transcriptional activation." (PMID 31555592, 2019). "To investigate whether the anti-leukemic effect of the drug is potentiated when combined with HDAC targeting, we tested the combination of CBL0137 and the HDAC inhibitor panobinostat in a highly aggressive, transplantable mouse model of MLL-AF9 (KMT2A:MLLT3) leukemia." (PMID 35677155, 2022). "Although MLL fuses with a variety of partners, most MLL fusion-mediated leukemia cases are caused by the fusions with the AF4 family (e.g., AF4 also known as AFF1, AF5Q31 also known as AFF4) and ENL family (e.g., ENL also known as MLLT1, AF9 also known as MLLT3)." (PMID 34431785, 2021).
leukemia (continued). "Interestingly, in KMT2A::MLLT3 rearranged MOLM13 cells the same analysis revealed predominant binding of DOT1L to promoter regions and no relevant association with putative enhancers indicating a function in MPN cells that is distinct from KMT2A-rearranged leukemia." (PMID 40781484, 2025). "We also detected the signature in some patients with KMT2A::MLLT1 or KMT2A::MLLT3 rearrangements, suggesting that the signature can be broadly applicable to KMT2A rearranged leukemia." (PMID 40646135, 2025). "In leukemia, the KMT2A gene is often translocated and fused to AFF1 (also known as AF4), MLLT1 (also known as ENL), or MLLT3 (also known as AF9)." (PMID 38426219, 2024). "Genomes with chromosomal rearrangements can also produce fusion circular RNAs (f-circRNAs) by backsplicing of chimeric transcripts, as first shown in leukemias with PML::RARα and KMT2A::MLLT3 translocations and later in solid cancers." (PMID 36585787, 2023). "Despite > 70 fusion partners of MLL1 were identified, only a few are frequently found in ~ 70% MLL1-r leukemias, including transcription cofactors AF9 (also known as MLLT3) and its paralog ENL (also known as MLLT1), AF4 and its paralog AFF4, and ELL." (PMID 35395864, 2022). "The combination of CBL0137 and panobinostat rapidly killed KMT2A-rearranged leukemia cells by apoptosis and significantly delayed leukemia progression and extended survival in an aggressive model of MLL-AF9 (KMT2A:MLLT3) driven murine acute myeloid leukemia." (PMID 35677155, 2022). "These core GRN factors are present in both AML and ALL leukemias and are targeted by both KMT2A-AFF1 and -MLLT3 fusion proteins." (PMID 34088716, 2021). "Another study by Wei and colleagues employed a murine xenograft model expressing the MLL-AF9 fusion gene (AF9, officially known as MLLT3) to demonstrate how niche-dependent processes affect the determination of lineage in leukaemia." (PMID 34713888, 2021). "We also implemented an oncogene-driven leukemia model (KMT2A::MLLT3) in which STAT5 is inactive and OSM is not induced." (PMID 41372120, 2025). "The conventional nested RT-PCR and/or karyotype method detected 240 rearrangements in the 319 patients with leukemia at diagnosis: 61 PML-RARa, 39 RUNX1-RUNX1T1, 32 CBFB-MYH11, 4 MLLT3-MLL, 1 DEK-NUP214, 61 BCR-ABL1, 12 MLL rearranged, 14 TEL-AML1, and 16 TCF3-PBX1." (PMID 25815789, 2015). "Identification of the KMT2A::MLLT3 fusion transcript indicated malignancy-associated HLH in the setting of evolving leukemia, even though the diagnosis of leukemia could not be made at that point." (PMID 40094975, 2025). "Understanding whether the H3K4 trimethylation activity of KMT2B is disturbed in KMT2A-rearranged leukemia, and particularly in context with KMT2A::AFF1 and KMT2A::MLLT3 fusion genes, represents an intriguing next chapter in illuminating the pathobiology of KMT2A-rearranged leukemia." (PMID 39834944, 2024). "In addition, we report several novel gene combinations (H1: CDCA7L-MLLT3, P3: SND1-TMEM178B), of which individual fusion partners have been previously reported in the context of several cancers, including MLLT3 in leukemia, SND1 (staphylococcal nuclease and tudor domain) in lung cancer." (PMID 32414213, 2020).
acute myeloid leukemia (114 papers, 2008 to 2026). Acute myeloid leukemia (AML) is a group of neoplasms arising from precursor cells committed to the myeloid cell-line differentiation. "One of the two most common fusion partners AF9 (official gene symbol: MLLT3) is involved in the primary translocation in the widely studied acute myeloid leukemia (AML) cell line, THP-1." (PMID 32719792, 2020). "We select six representative genes from CancerMine, which include three most frequently reported genes in the context of acute myeloid leukemia (AML), KMT2A, FLT3, and MLLT3, as well as three genes that are least reported in this specific cancer, namely ZFP36L2, ZIC2, and ZNF582." (PMID 38431735, 2024). "Acute lymphocytic leukemia gene 1 fused from chromosome 9 (AF9), also known as mixed lineage leukemia translocated to chromosome 3 homolog (Mllt3) is frequently found in balanced translocations with the mixed lineage leukemia gene (MLL), a trithorax homolog, in acute myeloid leukemia cells." (PMID 18554410, 2008).
acute leukemia (12 papers, 2013 to 2026). A clonal (malignant) hematopoietic disorder with an acute onset, affecting the bone marrow and the peripheral blood. "The MLL-MLLT3 gene fusion is the main mutation type of MLLT3 that drives tumorigenesis in acute leukemia." (PMID 28938601, 2017). "The most frequently found fusion partners of KMT2A in acute leukemia are the C‐terminal parts of AFF1, MLLT3, MLLT1 and MLLT10." (PMID 39887730, 2026).
acute promyelocytic leukemia (9 papers, 2013 to 2023). An aggressive form of acute myeloid leukemia (AML), characterized by arrest of leukocyte differentiation at the promyelocyte stage, due to a specific chromosomal translocation t(15;17) in myeloid cells. "In acute promyelocytic leukemia (APL) with PML::RARα translocations and acute myeloid leukemia with KMT2A::MLLT3 (MLL::AF9) fusions, f-circRNAs can be oncogenic or sustain the oncogenic properties of chimeric proteins." (PMID 36585787, 2023). "Importantly, PCR assays have been developed for three AML phenotypes: (i) acute promyelocytic leukemia (APL) (fusion gene PML::RARA); (ii) patients with NPM1 and CBF–AML (RUNX1::RUNX1T1 and CBFB::MYH11); and (iii) AML with fusion genes BCR::ABL1, KMT2::MLLT3, and DEK::NUP214." (PMID 37345204, 2023).
Ataxia (5 papers, 2019 to 2025). Ataxia refers to impaired coordination of voluntary muscle movement. "A loss-of-function mutation of the AF9/MLLT3 gene was hypothesized to relate to neuromotor development delay, cerebellar ataxia and epilepsy." (PMID 31805863, 2019). "Human patients presenting with complex neurological symptoms, including ataxia, revealed genomic deletions that included the MLLT3/AF9 locus." (PMID 30302725, 2019).
breast carcinoma (5 papers, 2019 to 2025). "BCL11A, MLLT3, ZNF521, PHC1, and PCGF3 also showed subtype-specific dysregulation in breast cancers; BCL11A, ZNF521, and PHC1 were specifically downregulated in luminal subtype cancers relative to their matched normal tissue." (PMID 39545637, 2024).
breast tumor (1 paper, 2020).
melanoma (1 paper, 2025). A malignant, usually aggressive tumor composed of atypical, neoplastic melanocytes. "Next, we analyzed the TCGA database to evaluate the RNA expression profile in order to better identify the underlying molecular targets of MLLT3 in melanoma." (PMID 39716999, 2025). "To further detect the underlying molecular target of MLLT3 in melanoma, we overlapped the result of ChIP‐seq and RNA‐seq data of MLLT3 and performed KEGG enrichment." (PMID 39716999, 2025). "The results still revealed that the OS of patients in the high‐risk score group is significantly lower than that in the low‐risk score group, and the OS, DSS and PFI of melanoma patients with low expression of MLLT3 were poor." (PMID 39716999, 2025). "To investigate the impact of MLLT3 on the prognosis of melanoma patients within a medium to short‐term period (within 10 years), we subsequently re‐analyzed the prognosis of high‐risk and low‐risk score groups, as well as the prognostic role of MLLT3 in melanoma patients." (PMID 39716999, 2025). "In order to investigate the effect of miR‐542‐3p and miR‐3922‐3p on melanoma cells, we transfected miR‐542‐3p and miR‐3922‐3p mimics into MLLT3 overexpressed A375 cells." (PMID 39716999, 2025). "This study further clarified the important role of MLLT3 in melanoma and explored its potential molecular mechanism, aiming to provide a new treatment strategy for melanoma." (PMID 39716999, 2025). "In vivo experiments also confirmed that overexpression of MLLT3 significantly reduced the growth of melanoma, the metastasis rate, and the expression of PCNA and CD133." (PMID 39716999, 2025). "To understand how MLLT3 regulate melanoma progression, we assessed the MLLT3 chromatin‐binding pattern in melanoma cells." (PMID 39716999, 2025). "This study demonstrates that MLLT3 is a transcription factor that regulates the stemness and progression of melanoma." (PMID 39716999, 2025). "Next, the effects of MLLT3 KO and overexpression on proliferative potential of melanoma cells were assessed by colony formation assay and Ki67 immunofluorescent staining." (PMID 39716999, 2025). "The results indicate that the transcription factor MLLT3 is a suppressor gene that regulates the stemness and progression of melanoma, and is expected to become a target for melanoma therapy." (PMID 39716999, 2025). "Taken together, our above results demonstrated MLLT3 was silenced by miR‐542‐3p and miR‐3922‐3p in melanoma cells." (PMID 39716999, 2025). "In this study, we identified MLLT3 as a cancer suppressor gene of melanoma based on a variety of research methods." (PMID 39716999, 2025). "To detect the interaction proteins of MLLT3 in melanoma, we transfected HEK‐293T cells with the Flag‐MLLT3 plasmid and then purified the MLLT3‐ interacting proteins for LC‐MS/MS analysis." (PMID 39716999, 2025). "We found that the transcription factor MLLT3 is an inhibitory gene that regulates the stemness, occurrence and development of melanoma." (PMID 39716999, 2025). "PCR and immunohistochemistry results also confirmed that MLLT3 was low expressed in melanoma tissues." (PMID 39716999, 2025). "RNA sequencing (RNA‐seq) analysis was carried out in A375 cells following MLLT3 overexpression in order to investigate the processes underpinning the impact of MLLT3 on melanoma progression." (PMID 39716999, 2025). "In conclusion, our results show that low expression of MLLT3 plays an important role in promoting malignant progression of melanoma, and is closely related to poor prognosis." (PMID 39716999, 2025). "In this study, we explored the effect of MLLT3 on melanoma through in vitro and in vivo experiments and clinical specimen analysis." (PMID 39716999, 2025). "In addition, overexpression of MLLT3 significantly inhibited the stemness, proliferation, invasion and metastasis of melanoma cells." (PMID 39716999, 2025).